TLR2 (toll like receptor 2)
Diseases named in the same sentence as TLR2 in open-access papers (continued):
Sharing a sentence is not in itself a finding about the gene and the disease.
glioma (continued). "Expression of TLR2 in microglia is necessary for the activation of MT1-MMP by neighboring glioma cells, and the process is MyD88 dependent." (PMID 25411122, 2014). "Consistent with our results, Li and colleagues demonstrated a significant increase in TLR2 expression in HGGs compared to LGGs, noting a positive correlation between TLR2 expression and tumor grade, and a role in promoting glioma development through enhanced autophagy." (PMID 40809181, 2025). "TLR2 activation in microglia has been shown to suppress CIITA and induce loss of MHC II expression via MAPK/ERK1/2 signaling, contributing to immune evasion in gliomas." (PMID 41157253, 2025). "In addition to glioma tissues, we observed significantly higher expression of TLR2 and TLR4 in epilepsy-derived tissues than in LGGs." (PMID 40809181, 2025). "Additionally, circulating immune cells (e.g., macrophages) and resident immune cells (e.g., microglia) with overexpressed TLR-2 and 5 were more successful in infiltrating and accumulating inflammatory immune responses against glioma invasion." (PMID 39202716, 2024). "We detected genes upregulated in PBT030 cells, such as SOX2, MYCN, NOS2, RUNX2, and VEGFA, while PBT147 cells upregulated level of PTEN, STAT6, CA9 and TLR2, demonstrating differences among PBT cell lines, which can be explained by various driving mutations and heterogeneity in glioma lines." (PMID 38449858, 2024). "While microglia in the healthy brain do not express MMP14, it is upregulated in glioma-associated microglia through TLR-2." (PMID 36768141, 2023). "Treatments targeting the expression or activation of TLR2 in GSCs within the glioma may be efficient strategies." (PMID 37723542, 2023). "The TLR2 gene was significantly over-expressed in the plasma samples of glioma patients." (PMID 34643804, 2022). "This reduction in glioma-derived IL-6, together with altered TLR2 signaling, could concomitantly hinder microglial MMP9 production." (PMID 35992852, 2022). "However, TLR2 upregulated MMP2 and MMP9 expression in GL261 glioma cell lines and promoted tumor invasion, indicating that TLR2 signaling in GSCs is involved in the invasiveness of glioma." (PMID 36611945, 2022). "Therefore, the implantation of mouse GL261 glioma cells into TLR2 knockout mice resulted in markedly smaller tumor volume and better survival rates compared with wild-type control mice." (PMID 35600367, 2022). "This idea is supported by a glioma model in which TLR2 knockout resulted in reduced glioma growth." (PMID 36224342, 2022). "The effects of activating TLR2 on glioma cells are complicated and sometimes contradictory." (PMID 33614649, 2021). "Finally, we showed that the effect of HMGB1 on glioma cells was mediated by TLR2, which activated Wnt/β-catenin signaling to promote GSCs." (PMID 33614649, 2021). "On the other hand, HMGB1 interacts with TLR2 on glioma cells to promote GSCs development and tumor progression via Wnt/β-catenin signaling, while their activation on DCs was shown to stimulate DC infiltration through activation of NF-κB, resulting in tumor suppression." (PMID 34715891, 2021). "The experiments using the GL261 glioma mouse model were prompted by our previous results on the promotion of tumor growth involving TLR2, TLR4, and TLR7 signaling, and were driven by the assumption that TLR5 might detect host-derived molecules." (PMID 32912327, 2020). "In the glioma context, TLR4 and in particular TLR2 are mediators of glioma-GAM interactions." (PMID 32331440, 2020). "In the present study, we tested whether O-Vanillin can be used to inhibit glioma-induced TLR2 signaling in murine microglia." (PMID 32331440, 2020). "Our results confirm that TLR2 is a candidate for adjuvant therapy in the treatment of glioma." (PMID 33155039, 2020).
glioma (continued). "Glioma cells expressing Toll-like receptor 2 (TLR2) ligands (e.g., heat shock proteins and extracellular matrix components) trigger the activation of microglial TLR2 and signaling through MAPK/ERK, leading to the deacetylation of histone H3K9." (PMID 35310881, 2020). "Furthermore, the presence of TLR2 was also detected in murine GL261 glioma cell line, and the activation of this receptor leads to an invasive and migratory profile of the tumor cells." (PMID 29912993, 2018). "In this study, a TLR1/TLR2 agonist enhanced the survival and function of administered T cells and altered the glioma microenvironment by simultaneously elevating the number of CD8+ positive T cells and down-regulating the number of immunosuppressive myeloid-derived suppressor cells (MDSCs)." (PMID 25411122, 2014). "In addition, TLR2 transcription is regulated by versican released from glioma cells." (PMID 38069210, 2023). "We also found that IDHmt gliomas had a higher proportion of GAMs with an M1‐like phenotype (IDHmt: IDHwt = 90.62%: 75.86%), as supported by an augmented proinflammatory signaling consisting of GAM‐associated cytokines and receptors, such as TNF, TLR2, and TNFRSF1B." (PMID 37166058, 2023). "TLR2 mRNA and protein levels in glioma tissues were found positively associated with glioma WHO histological grades and poor clinical outcome, and its overexpression could enhance glioma cell activity and cell cycle progression." (PMID 34715891, 2021). "Thus, TLR2 has emerged as a novel target for impairing glioma growth and we could demonstrate in a mouse glioma model that interfering with TLR2 signaling by using TLR2—specific antibodies attenuated glioma growth." (PMID 32331440, 2020). "al. demonstrated that MMP9 is predominantly expressed by glioma-associated microglia/macrophages in mouse and human glioma tissue not by glioma cells, and glioma-associated microglial MMP9 expression is upregulated by TLR2 signaling and is sensitive to minocycline." (PMID 27022952, 2016). "Our research underscores the varying levels of TLR2 and TLR4 expression in gliomas and epilepsy, with TLR2 showing a significant increase in HGGs and both TLRs exhibiting marked elevation in epilepsy tissues compared to LGGs." (PMID 40809181, 2025). "The expressions of TLR2 and TLR4 have been previously examined in clinical glioma tissues and glioblastoma U87 cell lines." (PMID 40809181, 2025). "In a mouse glioma model called GL261, TLR2 activation with a synthetic bacterial lipoprotein in conjunction with tumor antigen-specific CD8 T cells improved long-term survival and immunological memory." (PMID 40727443, 2025). "The expression of TLR2 and TLR4 was significantly greater in the epilepsy group compared to the low-grade glioma group." (PMID 40809181, 2025). "TLR2 and TLR4 were shown to be up-regulated in glioma samples and are negatively correlated with poor prognosis." (PMID 40809181, 2025). "Previous studies have reported increased TLR2 expression in advanced ovarian cancer patients, and abnormal FADD expression has been noted in various solid tumors, including glioma, non-small cell lung cancer (NSCLC), and hepatocellular carcinoma (HCC)." (PMID 39669578, 2024). "In mouse glioma models, high-mobility group box 1 (HMGB1), an alarmin produced by dying cancer cells, activates TLR2 in dendritic cells (DCs) and leads to brain tumor regression." (PMID 39594997, 2024). "Despite the strong evidence for the role of TLR2/4 signaling in cancer immune response, the importance of the gut microbiota in modulating the TLR signaling in glioma is largely unexplored." (PMID 39594997, 2024). "In particular, the TLR families, including TLR1, TLR2, TLR3, TLR4, TLR6, and TLR9, are highly expressed in the TME of glioma, both in vitro and in vivo, leading to neuroinflammation." (PMID 37723542, 2023).
glioma (continued). "This is accompanied by an upregulation of its TLR1 and TLR2 expression and mediates an increase in MMP-9/MMP-14 expression, promoting microglia-mediated glioma progression." (PMID 37700840, 2023). "Other factors that promote glioma progression and invasiveness include epidermal growth factor (EGF) expression, stress-inducible protein 1 (STI1) expression and Toll-like receptor 2 (TLR2) upregulation." (PMID 38275375, 2023). "The GL261 glioma cell line and activation of TLR2 upregulated the expression of MMP2 and MMP9 to promote tumor invasion, indicating that TLR2 signaling in glioblastoma stem cells (GSCs) is involved in the invasiveness of glioma." (PMID 36611945, 2022). "We combined all tumor expression data from TCGA with GEPIA2 data and obtained differentially expressed genes that were correlated with CASP4 expression in gliomas, including GSDMD, CASP1, IL-18, and TLR2." (PMID 36713560, 2022). "It is interesting to note that, upon direct TLR2 stimulation, CD44-/- microglia were still able to increase MMP9 production, while this ability was completely abolished in the presence of glioma cells." (PMID 35992852, 2022). "Up to date, TLR2, TLR3, TLR4, TLR7, and TLR9 have been intensely studied in glioma, while less or missing information is available regarding the mechanisms of TLR1/TLR6 (dimerizes with TLR2), TLR5, TLR8 (dimerizes with TLR7), and particularly TLR10." (PMID 34715891, 2021). "TLR2 upregulates membrane type 1 matrix metalloprotease (MT1-MMP) and metallopeptidase 14 (MMP14) in MG to activate glioma-sourced MMP2 when responding to TLR2 endogenous ligands and thereby facilitate glioma invasion." (PMID 34671362, 2021). "In glioma, elevated TLR1, TLR2, TLR4, TLR5, TLR6, and TLR9 expressions were observed in tumor cell lines and tissues compared with non-neoplastic brain tissues, particularly in the mesenchymal subtype of GBM." (PMID 34715891, 2021). "TLR2 overexpression also enhanced cell autophagy and modulated p38/MAPK pathway, which in turn contributed to viability of glioma cells." (PMID 34715891, 2021). "TLR2 promotes TAM production of MMP14, which is essential for MMP2 release and glioma invasion, and the microglial expression of the metalloprotease MT1-MMP, which cleaves the pro-MMP2 into its active form, resulting in tumor invasion." (PMID 33766119, 2021). "In the present study, we used in vitro and in situ microglia-glioma interaction experimental models to test the impact of a novel inhibitor of TLR 2, ortho vanillin (O-Vanillin) to block TLR2 mediated microglia protumorigenic phenotype." (PMID 32331440, 2020). "Previously, GL261 cells have also been shown to express TLR2, TLR3 and TLR4, and TLR ligands have been used as treatments against established glioma." (PMID 30974896, 2019). "Agonists of TLR2 (Pam3CSK4 and MALP2) induce the upregulation of MT1-MMP expression, promoting glioma expansion and progression." (PMID 31240216, 2019). "In a study, it has been revealed that dying glioma cells release HMGB, thus stimulating TLR2-dependent NFkB signaling and denderetic cells activation." (PMID 27040385, 2016). "In other experiments, endogenous TLR2 agonist HMGB1, released from glioma cells by targeted treatment with gancyclovir, activated DCs and facilitated therapy." (PMID 25411122, 2014). "TLR2, TLR4, and TLR9 have been under investigation for expression on glioma cells, and their contribution to tumor development has been mostly described as tumor promoting." (PMID 25411122, 2014). "Bacterial lipoprotein (TLR2 agonist) administered with antigen-specific T cells achieved long-term survival and immune memory in the murine GL261 glioma model." (PMID 25411122, 2014). "Moreover, TLR2, TLR3, TLR4, TLR7, TLR8, and TLR9 have emerged as critical modulators of glioma biology." (PMID 41157253, 2025).
glioma (continued). "When TLR2 was absent from mice implanted with GL261 glioma cells, the tumors were significantly smaller, the expression of membrane type 1 matrix metalloprotease (MT1-MMP) was decreased, and the survival rates were higher than in wild-type control mice." (PMID 40727443, 2025). "Additionally, TLR2 activation can upregulate MMP1 expression in microglia and gliomas, promoting tumor growth and migration." (PMID 39458936, 2024). "The upregulation of TLR-2 on the glioma cell membrane facilitates cell proliferation because the innate immune cells did not attack (phagocytosis) the glioma cells." (PMID 37833789, 2023). "In addition, treatment with TLR2-neutralizing antibodies reduced glioma-induced microglial MT1-MMP expression and attenuated glioma growth." (PMID 35600367, 2022). "In addition, for TLR2, in the glioma TME, TLR2 activation in microglia induces downregulation of MHC class II expression in microglia, thereby limiting T cell-dependent antitumor immunity and promoting glioma immune evasion." (PMID 36365103, 2022). "It was reported that TLR2 activation with a synthetic bacterial lipoprotein administered jointly with tumor antigen-specific CD8 T cells increased long-term survival and immune memory in a murine glioma model GL261." (PMID 31240216, 2019). "In murine GL261 glioma cells implanted in TLR2 knockout mice, the lack of TLR2 resulted in significantly smaller tumors, reduced membrane type 1 matrix metalloprotease (MT1-MMP) expression, and enhanced survival rates compared with wild-type control mice." (PMID 31240216, 2019). "Glia, neurons, and neural progenitor cells all express TLR2 and TLR4, and may contribute to the striking responsiveness of several glioma models to metronomic CPA-induced anti-tumor immunity seen in our studies." (PMID 25952672, 2015). "Toll-like receptor 2, one of the HMGB receptors, is believed as correlation with NETs production, and HMGB1-mediated TLR2 signaling plays a critical role in eliciting glioblastoma regression, However, further studies are still needed to clarify the protumor and antitumor functions of NETs in glioma." (PMID 35711434, 2022). "This follows release of HMGB1, a TLR2 agonist that activates dendritic cells and stimulates dendritic cells loaded with glioma antigens to migrate to the cervical lymph nodes to prime a systemic CD8+ T cytotoxic killing of glioma cells without causing brain toxicity and autoimmunity." (PMID 31069169, 2019). "Within the family of TLRs, TLR-2, TLR-4, and TLR-9 stand out with unique expression patterns in glioma cell lines, while TLR-7 and 8 remain absent in gliomas." (PMID 39202716, 2024).
colorectal cancer (55 papers, 2004 to 2025). A primary or metastatic malignant neoplasm that affects the colon or rectum. "TLR2 (Delta22) polymorphisms were linked to an increased risk of gallbladder cancer, while TLR2 microsatellite GT polymorphism has been linked to sporadic colorectal cancer in Croatians." (PMID 39071840, 2024). "In the gut, specific Tlr2 polymorphisms have protective effects while others are associated with an increased risk of colorectal cancer depending on the populations." (PMID 33408714, 2020). "We investigated the expression levels of TLR2 and associated-miRNAs in colorectal carcinoma (CRC) tissues and cell lines using real-time PCR, northern blotting and western blotting." (PMID 23866094, 2013). "However, previous research indicated that overexpression of TLR2 was associated with a high risk of colorectal cancer, cervical cancer, and oral cancer." (PMID 36120433, 2022). "The results indicated that HCMV infection may be associated with colorectal cancer and adenoma and inflammatory responses may be mediated by the TLR2 or TLR4 signaling pathways." (PMID 25435993, 2015). "Elevated levels of this genus in the gut have been shown to co-localize with cancer-associated fibroblasts (α-SMA+) and activate the TLR2/NF-κB signaling pathways, contributing to the reduction of CD8+ T cells in the colorectal cancer microenvironment." (PMID 40869289, 2025). "Upon recruitment to the TME by colorectal cancer cells, TAMCs facilitate colorectal cancer growth and metastasis via TLR-2-mediated activation." (PMID 38520648, 2024). "Gene knockout and knockdown of TLR2 can inhibit the proliferation of inflammation-related colorectal cancer and sporadic colorectal cancer." (PMID 35733095, 2022). "TLR2 signaling has been reported to have a protective role in inflammatory conditions and colorectal cancer, and to promote immune homeostasis by inhibiting the expression of pro-inflammatory cytokines and enhancing IL-10 production." (PMID 36439842, 2022). "In colorectal cancer, TLR2 is expressed at high levels by most tumor cells, which is often as a consequence of the loss of the hypermethylated in cancer 1 (HIC1) tumor suppressor gene that normally inhibits its transcription." (PMID 33321934, 2020). "This suggests that knockdown of TLR2 gene expression can inhibit the proliferation of colorectal cancer cells, leading to cell cycle arrest in the G1 phase and thereby significantly inhibiting the sCRC cell cycle." (PMID 32256204, 2020). "High levels of TLR2 expression in tumor tissues of colorectal cancer (CRC) patients have been reported." (PMID 32256204, 2020). "Clinical trials of TLR2 agonists as anticancer therapeutics have been limited but have suggested efficacy in patients with pancreatic and colorectal cancer." (PMID 32696994, 2020). "Knockout and knockdown of TLR2 can inhibit the proliferation of inflammation-related colorectal cancer and sporadic colorectal cancer." (PMID 32256204, 2020). "Lentivirus carrying TLR2-RNAi was used to stably infect colorectal cancer cells (HCT116 and HT29) to knock down TLR2 gene expression." (PMID 32256204, 2020). "It is clear that TLR2 plays an important role in the pathogenesis and development of colorectal cancer." (PMID 32256204, 2020). "More interestingly, TLR2’s promoting effect on colorectal cancer cell proliferation was shown by a recent study to be dependent on PI3K/Akt and NF-κB signaling pathways, which is inspiring for future studies on more detailed molecular pathways." (PMID 31675995, 2019). "The aim of this study was to investigate TLR2 (-196 to-174del), TLR4 (Asp299Gly and Thr399Ile) and TLR9 (T1237C and T1486C) gene polymorphisms at risk of colorectal cancer (CRC) development and progression." (PMID 29883450, 2018). "To understand the mechanism, we examined the expression levels of Fas, c-Jun and TLR2 of the four types of colorectal carcinoma cells." (PMID 29079852, 2017).